TNF (tumor necrosis factor)
Diseases named in the same sentence as TNF in open-access papers (continued):
Sharing a sentence is not in itself a finding about the gene and the disease.
cardiac arrest (28 papers, 2009 to 2025). Cessation of breathing and/or cardiac function. "Inflammatory cytokines, such as IL-6, IL-10, and TNF-α, have been associated with cardiovascular dysfunction in patients with cardiac arrest." (PMID 33510459, 2021). "On the other hand, adiponectin secreted by visceral fat inhibits the release of pro-inflammatory molecules such as interleukin-6 (IL-6) and tumor necrosis factor-α (TNF-α) after cardiac arrest, alleviating systemic inflammatory responses." (PMID 41450519, 2025). "IL-6 and TNFα expression have been found to be involved in inflammation due to tissue hypoxia after cardiac arrest." (PMID 37790622, 2023). "Previous research demonstrated that GLC treatment reduced tumor necrosis factor (TNF)-α, interleukin (IL)-6, and NF-κB following experimental cardiac arrest." (PMID 34512312, 2021). "In agreement with this, TNF-α levels in blood was found to increase during recovery from cardiac arrest in swine model and the increment of TNF-α levels were associated with depression of left ventricle function." (PMID 32293300, 2020). "Cardiac arrest dramatically induced immediate mediators of neuroinflammation such as IL1β, TNFα, and iNOS." (PMID 28957432, 2017). "TNFα and IL-4 were identified as important cytokines in both “cardiac arrest group” skin and muscle and are known to play a role in many immune regulation or intercellular signaling contexts." (PMID 26635801, 2015). "IL-4, IL-12p70, and TNFα were expressed at significantly different levels between skin and muscle tissues within the “cardiac arrest group” animals." (PMID 26635801, 2015). "This is emphasized by the data of Mizushima and colleagues who demonstrated that the integrity of the blood-spinal cord and blood-brain barriers to radiolabelled TNFα remains intact following resuscitation in a mouse model of cardiac arrest." (PMID 20158893, 2010). "Due to cardiac arrest and cerebral ischemia also the expression of TNFα gets up-regulated." (PMID 37790622, 2023). "Similarly, the inhalation of 40 or 80 ppm H2S attenuates the pro-inflammatory response induced by interleukin (IL)-1β, IL-6, and tumor necrosis factor-alpha (TNF-α) in rats after cardiac arrest and cardiopulmonary resuscitation." (PMID 33672103, 2021). "Thereby, we could show that TNF-alpha and IL-8 mRNA levels were expressively high immediately after cardiac arrest followed by a significant decrease over the next 72 hours." (PMID 29445259, 2017). "Similarly, there was less TNF-α production induced in Pam3CSK4-activated whole blood samples taken from patients after cardiac arrest." (PMID 27260481, 2016). "After cardiac arrest, blood concentrations of most of the investigated cytokines increased in the Control group, except for CD31 and TNF-α." (PMID 38954057, 2024). "Serum levels of oxidative stress products (8-iso prostaglandin F2 alpha and MDA) and inflammatory cytokines (TNF alpha, IL-1 beta, and HMGB1) are increased at 3, 12, and 24 h after cardiac arrest." (PMID 36101338, 2022). "Cardiac arrest and ECPR markedly increased the plasma levels of IL-10, VEGF, leptin, TNF-α, IL-1β, IL-6, fractalkine, IL-5, IL-18, IP-10, IL-4, eotaxin, MIP-1α, IL-17α, IL-12, RANTES, G-CSF, LIX, and MCP-1." (PMID 34781966, 2021). "In accordance to our findings, levels of TNFα were higher in male pigs than in female swine after resuscitation from cardiac arrest, and this effect was not related to steroid hormones." (PMID 37138659, 2023). "Elevated levels of Interleukin (IL)-6, IL-8 and TNF-α as well as of IL-1Ra and IL-10 have been observed in patients with poor neurological outcome and in non-survivors after cardiac arrest." (PMID 33141843, 2020). "In the brain 2 h post-ROSC, cardiac arrest and CPR led to an increase in the mRNA levels of IL-6, IL-1β, and TNF-α, but not HMGB-1." (PMID 35011872, 2021).
colorectal adenocarcinoma (28 papers, 2013 to 2025). The most common type of colorectal carcinoma. "To study the molecular mechanisms underlying IEC death, we tested whether LT + TNF-induced IEC death can be reproduced in human colorectal adenocarcinoma cell line HT-29." (PMID 37855658, 2024). "TNFα expression is also associated with tumor progression of colorectal adenocarcinomas." (PMID 23431386, 2013). "This study aimed to examine the properties of three probiotic strains using the tumor necrosis factor-alpha (TNF-α) inhibition test in colorectal adenocarcinoma cells (Caco-2 cells)." (PMID 36986118, 2023). "Firstly, the suitability of the human colorectal adenocarcinoma cell line Caco-2 was investigated in terms of its change in barrier properties after stimulation with the pro-inflammatory cytokine TNF-α in different concentrations." (PMID 37520160, 2022). "Cytosolic RARγ has also been shown to be pivotal to tumor necrosis factor (TNF)-induced cell death of HT-29 colorectal adenocarcinoma cells." (PMID 36204679, 2022). "To find the mechanism by which HtrA2 regulates necroptosis, we treated HT-29, a type of colorectal adenocarcinoma cell, with TNF-α plus Smac mimetic and Z-VAD (T/S/Z) in vitro." (PMID 31019191, 2019). "F. nucleatum induces IL-8, IL-1β, TNF-α, and ROS generation in Caco-2 colorectal adenocarcinoma cells by impairing autophagic flux." (PMID 31737164, 2019). "In trefoil factor 3 (TFF3) overexpressing colorectal adenocarcinoma cells (HT-29/B6), we observed enhanced resistance against TNF-α/interferon gamma-induced apoptosis." (PMID 28149533, 2017). "To address this, we used TFF3-overexpressing colorectal adenocarcinoma cells (HT-29/B6/TFF3) as a model for scattering cancerous cells that are protected from IFN-γ/TNF-α-induced apoptosis." (PMID 28149533, 2017). "In cells such as the HT29 colorectal adenocarcinoma, necroptosis can be triggered by tumor necrosis factor alpha (TNF-α) stimulation when caspases and translation are inhibited." (PMID 27602963, 2016). "Finally, the pollen anti-inflammatory potential has been assessed on a TNFα-inflamed human colorectal adenocarcinoma cell line (HT-29)." (PMID 36670977, 2023). "Finally, we also assessed its anti-inflammatory potential on an inflamed human colorectal adenocarcinoma cell line (HT-29) exposed to the tumor necrosis factor-alpha (TNF-α) used to induce inflammation." (PMID 36670977, 2023). "Together, these data confirm previous results showing that inflammatory stimuli can trigger AID expression in cell lines originated from human colorectal adenocarcinoma, and show that pancreatic adenocarcinoma cells and primary pancreatic cells are also responsive to TNF-α treatment." (PMID 26282919, 2015). "Thus, the expression of IL-1β and TNF-α could be largely suppressed in colorectal adenocarcinoma in mice by treatment with a combination of zotarolimus and 5-FU." (PMID 34361836, 2021). "We additionally analyzed MNNG- and TNF-induced activation/disappearance of PARP-1, depletion of intracellular ATP and loss of membrane integrity in human leukemic Jurkat T cells and human HT-29 colorectal adenocarcinoma cells as two additional established cell systems for necroptosis." (PMID 23760205, 2014). "The increased secretion of pro-inflammatory cytokines such as, IL-1β, IL-6, and TNF-a in macrophages (THP-1 cell lines) or IL-6, IL-8, and TNF-a in human colorectal adenocarcinoma cells (Caco-2 cells) was observed following exposure to 59 nm or 100 μm PS." (PMID 39120391, 2024). "Furthermore, in several cell culture models of intestinal dysfunction, established with human colorectal adenocarcinoma cells, PAs from various sources could decrease the level of inflammatory mediators (e.g., TNF-α, IL-6 and IL-8) and had a protective effect on the cell layer integrity." (PMID 35052987, 2022).
colorectal adenocarcinoma (continued). "In two human colorectal adenocarcinoma lines, HT-29 and COLO 205, that are sensitive to necroptosis induced by treatment with TNFα, zVAD-fmk, and cIAP inhibitor BV6, multiple sgRNAs targeting PTBP1 enhance inclusion of the RIPK1 alternative exon." (PMID 29449584, 2018). "Similar anti-inflammatory effects of the fungal metabolites were observed in the human colorectal adenocarcinoma cell line DLD-1 after stimulation with IFN-γ (10 ng/ml), TNF-α (10 ng/ml), and IL-1β (5 ng/ml)." (PMID 28824460, 2017). "We found that TPKC also significantly diminished TNF-induced necroptosis in murine NIH3T3 fibroblasts cells as well as in human leukemic Jurkat T cells and in human HT-29 colorectal adenocarcinoma cells as further established cell systems for necroptosis." (PMID 24090154, 2013).
keratoconus (28 papers, 2010 to 2026). A degenerative, structural disorder of the eye, characterized by a cone-shaped protrusion of the cornea. "A presumed progression risk factor of keratoconus is the contact lens wear, especially rigid gas permeable contact lenses that induce the upregulation of IL-6, TNF-alpha, ICAM-1, and VCAM-1 in the tears of subjects with keratoconus." (PMID 27563164, 2016). "For instance, analysis of tear film components in keratoconus has revealed candidate biomarkers: elevated levels of certain cytokines (IL-6, TNF-α), MMPs, and specific microRNAs." (PMID 41595486, 2026). "For example, concentrations of IL-6, IL-8, IL-1β, and TNF-α are markedly elevated in keratoconus patients relative to healthy controls." (PMID 40547926, 2025). "The use of Spearman correlation matrices further revealed stronger and more coordinated cytokine co-regulation in the stable keratoconus group compared to healthy controls, particularly involving IL-6, IL-1β, and TNF-α." (PMID 40980981, 2025). "Stable keratoconus patients displayed stronger positive correlations among multiple cytokines, particularly IL-6, IL-1β, and TNF-α, indicating a more coordinated inflammatory network." (PMID 40980981, 2025). "We observed significantly higher levels of IL-1β, IL-10, IFN-γ and TNF-α in moderate and severe keratoconus than in mild keratoconus (p < 0.05)." (PMID 38256126, 2024). "In fact, proinflammatory cytokines (IL-1, IL-6, TNF-α, and TGF-β), oxidative stress, or degradation of collagens by metalloproteases (MMP-1, MMP-3, and MMP-9) has been implicated in keratoconus pathophysiology." (PMID 35075374, 2022). "On the contrary, multiple recent studies published evidence that highlight a possible inflammatory etiology marked through the presence of proinflammatory cytokines such as IL-6, IL-1 beta, IFN gamma, and TNF alpha in the tear film of keratoconus patients." (PMID 30245588, 2018). "The means of IFN gamma, IL-10, IL-1 beta, IL-4, IL-6, and TNF alpha had a significant difference between the keratoconus patients and the normal subjects." (PMID 30245588, 2018). "Our aim was to determine the concentration of IL-4, IL-6, IL-10, RANTES, IFN gamma, and TNF alpha in the tear film of patients with keratoconus and their first degree family members." (PMID 30245588, 2018). "They observed increased levels of MMP-9, tumor necrosis factor, and interleukin-6 in the tear film of patients with keratoconus and overexpression of IL-6 and TNF-alpha in the tears of subclinical keratoconic patients." (PMID 27563164, 2016). "Enzyme linked immunosorbent assay (ELISA) analysis of capillary collected tears in 28, 30 and 94 patients with keratoconus in three different studies showed elevated levels of inflammatory markers IL-6, TNFα and MMP9." (PMID 27493978, 2016). "Partly in line with these results, increased tear levels of MMP-1, MMP-3, MMP-7, MMP-9, and MMP-13; IL-4, IL-5, IL-6, and IL-8, and TNF-α, -β were found in keratoconus." (PMID 26881061, 2016). "Recent studies have suggested pro-inflammatory factors as key to keratoconus pathogenesis based on their findings of elevated interleukin (IL)-6, tumor necrosis factor (TNF)-α and matrix metalloproteinase (MMP)-9 in the tear fluid of keratoconus patients." (PMID 21298010, 2011). "Others have examined isolated cytokines by conventional sandwich ELISA and reported concentrations of IL-6, TNF-α and IL-10 in control and keratoconus subjects." (PMID 21298010, 2011). "Our findings confirm increased IL-6, but dispute earlier reports of increased TNF-α, and suggest a cytokine imbalance in keratoconus disrupting corneal homeostasis." (PMID 21298010, 2011). "Keratoconus, with a similar inflammatory profile to that of ocular surface disease, has elevated Interleukin (IL)-1β, IL-6, tumor necrosis factor (TNF)-α, and matrix metalloproteinase (MMP)-9, contributing to extracellular matrix degradation and stromal thinning." (PMID 40993744, 2025).
keratoconus (continued). "Numerous studies have identified altered cytokine expression in the tear fluid and corneal epithelium of keratoconus patients—particularly IL-6, TNF-α, and IL-1 family members—supporting a model of localized inflammation contributing to stromal degradation and extracellular matrix remodeling." (PMID 40980981, 2025). "Interestingly, we observed a significantly higher level of IL-1β, IL-10, IFN-γ, and TNF-α with moderate and severe keratoconus than with mild keratoconus." (PMID 38256126, 2024). "Analyses of tears and corneal tissue in patients with keratoconus have shown an increase in several cytokines, including IL-6, IL-8, IL-1β, TNF-α, and IFN-β, which may support this hypothesis." (PMID 38203537, 2023). "Moreover, overexpression of IL-6 and TNF-α in tears of subclinical keratoconus indicate that chronic inflammatory events are involved in the pathogenesis of keratoconus." (PMID 36904299, 2023). "Thus, a variety of matrix metalloproteinases (MMP) -1, -3, -7, -13, interleukins (IL) -4, -5, -6, -8, and tumor necrosis factor (TNF) -α and -β are elevated in keratoconus tears." (PMID 27493978, 2016). "IL-4, Il-12, IL-13, and TNF-alpha were found to be downregulated in the keratoconus group." (PMID 27563164, 2016). "Besides, tear cytokines IL -4, -5 and -6, and TNFα, which were elevated in keratoconus, were also shown to have similar expressions in DES, indicating certain similar molecular changes among the two disease conditions." (PMID 27493978, 2016). "In severe keratoconus, IL-12 and TNF-α decreases were more pronounced and this may play a role in increased IL-17 and associated tissue degenerative processes." (PMID 21298010, 2011). "Also, TNF-alpha and IL-6 can also be found in atopic and vernal keratoconjunctivitis, suggesting that keratoconus could be related to allergies and to increased level of serum IgE." (PMID 27563164, 2016). "Increased levels of inflammatory mediators such as IgE, cytokines (IL-1, IL-6 and TNF-alpha) and proteolytic enzymes (MMP-9) have been found in the tears of keratoconus patients." (PMID 36138270, 2023). "Increased levels of inflammatory mediators, such as immunoglobulin E (IgE), cytokines (IL-1, IL-6 and TNF-alpha) and proteolytic enzymes (MMP-9), have been found in the tears of keratoconus patients." (PMID 36138270, 2023). "To address this controversial issue at the single-cell level, we first surveyed the predominant source of several reported cytokines increased in keratoconus samples, including IL1, IL6, IL10, TNF-α and TGF-β37,75,76." (PMID 35821117, 2022). "Altered corneal epithelial and stromal expressions of specific genes, such as tumor necrosis factor-α (TNF-α), interleukin-1 (IL-1), IL-6, and matrix metalloproteinase 9 (MMP-9), were also found at the corneal cone apex in keratoconus." (PMID 35692541, 2022). "Interleukin (IL)-1β, IL-4, IL-6, IL-10, IL-12, IL-13, IL-17, interferon (IFN)-γ, chemokine C-C motif ligand 5 (CCL5) and tumor necrosis factor (TNF)-α were tested in tear samples and sera of keratoconus and control individuals by multiplex immuno-bead assays." (PMID 21298010, 2011). "The decreases in IL-12, TNF-α and CCL5 were statistically significant, while the IL-13 decrease was statistically significant in the severe keratoconus group only." (PMID 21298010, 2011). "The multiplex data implicate reductions in TH1 (IL-12, TNF-α, IFN-γ), and possibly TH2 cytokines (IL-4 and IL-13) in keratoconus." (PMID 21298010, 2011). "IL-12 promotes the differentiation of TH1 cells; its decrease in keratoconus is consistent with decreases in two signature TH1 cytokines, IFN-γ and TNF-α." (PMID 21298010, 2011). "Values below the LLOQ were observed rarely: 12.5% (n = 6, three in each group) for IFN-γ, 4.17% (n = 2, both in the keratoconus group) for IL-17A, 2.08% (n = 1 in the control group) for TNF-α and never for the remaining cytokines." (PMID 40980981, 2025).
keratoconus (continued). "By correlating corneal and immunological data, we observed significantly higher levels of IL-1β, IL-10, IFN-γ and TNF-α in moderate and severe keratoconus than in mild keratoconus (p < 0.05), but not exceeding the values in the control group." (PMID 38256126, 2024). "More recently, Lema and Durán targeted specific cytokines, cell adhesion molecules, and proteases in patients with keratoconus, and found levels of IL-6, TNF-α, and MMP-9 higher in keratoconus subjects as compared to normals." (PMID 21031023, 2010). "These factors may contribute to the pathogenesis of keratoconus; furthermore, studies have shown that post-rubbing tear samples from normal eyes exhibit high concentrations of IL-8, MMP-13, IL-6, TNF-α, and epithelial growth factor compared to contralateral control eyes." (PMID 40343259, 2025). "Elevated levels of interleukin- (IL-) 1b, IL-4, IL-5, IL-6, IL-8, and IL-17; tumor necrosis factor (TNF)-α, -β; interferon- (IFN-) γ; matrix metalloproteinase- (MMP-) 1, MMP-3, MMP-7, MMP-9, and MMP-13; Cathepsin B; and Lipocalin-1 have been found in the tears of patients with keratoconus." (PMID 26881061, 2016). "The study showed increased levels of gelatinases and collagenases (1.9 times higher), as well as elevated MMPs, cytokines (MMP-1, MMP-3, MMP-7, MMP-13, and IL-6), and TNF-alpha and TNF-beta in the keratoconus group compared with the normal group." (PMID 27563164, 2016).